UCP2 (uncoupling protein 2)
Diseases named in the same sentence as UCP2 in open-access papers (continued):
Sharing a sentence is not in itself a finding about the gene and the disease.
steatosis (17 papers, 2012 to 2024). Increased lipid within the cytoplasm of cells. "Studies on different tissues of animal models confirmed that the baseline expression of UCP2 gene in hepatocytes is undetectable but it shows significant up-regulation in the liver during pathologic conditions associated with steatosis." (PMID 24638096, 2014). "When the hydrogen gas was inhaled, hepatocyte steatosis was reduced, and the UCP2 expression level in liver tissue was increased." (PMID 34943036, 2021). "Early upregulation of uncoupling protein-2 (UCP-2) during steatosis protects hepatocytes against ROS production through ATP production, whereas a further increase in UCP-2 during NASH leads to chronic ATP depletion." (PMID 33371482, 2020). "In addition, in the early stage of steatosis, the up-regulation of UCP2 can inhibit a large amount of ROS damage and play a protective role in cells." (PMID 37373507, 2023). "Besides, UCP-2 plays a protective role through ameliorating oxidative stress role in palmitate-induced hepatocytic steatosis." (PMID 33425805, 2020). "Indeed, we observed increased lipid peroxidation and UCP2 expression as oxidative markers also in the liver of ACE2−/y mice suggesting that steatosis is accompanied by elevated oxidative stress in these animals." (PMID 28101297, 2016). "Moreover, the specific inhibition of UCP2 by genipin remarkably exacerbated PA-induced hepatocytes steatosis." (PMID 23151243, 2012). "Therefore, the role of UCP2 in steatosis is controversial and may require cell-specific investigations." (PMID 34829779, 2021). "Berberine can also reduce the expression of uncoupling protein-2 (UCP2) and UCP2 mRNA in liver tissue, improve hepatocyte steatosis, and improve lipid metabolism disorders." (PMID 37570615, 2023). "Meanwhile, in the cultured steatosis LO2 cells, a decline was observed in the activities of CPT-1 and UCP2, the activities of which were significantly enhanced after taurine administration." (PMID 37373507, 2023). "BBR can downregulate hepatic expression of uncoupling protein-2 (UCP2) mRNA protein in NAFLD rats, promote the recovery of hepatocyte steatosis, and improve lipid metabolism disorder." (PMID 23843872, 2013). "Previous studies, however, have found no impact of UCP2 KO on the presence or progression of steatosis in the livers of diet-induced obese mice." (PMID 34829779, 2021). "Unfortunately, no changes were observed after pterostilbene treatment, meaning that, irrespective of the positive or negative effect of UCP2 on steatosis, the delipidating effect of this phenolic compound was not mediated by this uncoupling protein." (PMID 31035507, 2019). "Combined exposure to NP and HSHFD induced macrovesicular steatosis with dilation and congestion of the central vein, liver inflammatory cell infiltration, and expression of genes regulating lipid metabolism, SREBP-1C, FAS, and Ucp2." (PMID 29459774, 2018). "Unfortunately, no changes were observed after resveratrol treatment, meaning that irrespective of the positive or negative effect of UCP2 on steatosis, the delipidating effect of this phenolic compound was not mediated by this uncoupling protein." (PMID 28696376, 2017). "In addition, the expression of the UCP2 was significantly higher in ACE2−/y mice compared to WT at mRNA and protein levels at both ages, suggesting that the steatosis is accompanied by oxidative stress." (PMID 28101297, 2016). "However, the role of UCP2 in hepatocytes steatosis has not been determined." (PMID 23151243, 2012).
Cerebral ischemia (16 papers, 2009 to 2025). Restriction of arterial blood supply to the brain associated with insufficient oxygenation to support the metabolic requirements of the tissue. "UCP2 deficiency has been shown to cause an increase in resistance to cerebral ischemia, with an increase in cerebral neuronal antioxidant status." (PMID 35159548, 2022). "Mitochondrial uncoupling protein 2 (UCP2) deficiency exacerbates brain damage following cerebral ischemia/reperfusion (I/R)." (PMID 33735403, 2021). "Pronounced lucency and disarray and disappearance of mitochondrial cristae were observed, suggesting that UCP2 deletion increases mitochondrial morphological damage caused by cerebral ischemia in both normo- and hyperglycemic animals." (PMID 33061796, 2020). "We have demonstrated previously that the PPARγ agonist, rosiglitazone enhances UCP2 expression in the hippocampal neurons, leading to protection against oxidative stress and neuronal cell death associated with cerebral ischemia." (PMID 22849356, 2012). "In models of cerebral ischemia-reperfusion, mice overexpressing UCP-2 exhibit less neuronal damage and lower ROS levels." (PMID 39281670, 2024). "UCP-2’s neuroprotective effect is believed to stem from its antioxidant properties, which help reduce oxidative stress during cerebral ischemia-reperfusion." (PMID 39281670, 2024). "In some mouse and rat models of cerebral ischemia, overexpressed UCP2 plays a neuroprotective role by regulating the expression of Bcl-2 family proteins and cell survival factors." (PMID 34658794, 2021). "Collectively, deletion of UCP2 has an adverse impact on cerebral ischemia-reperfusion injury under both normo- and hyperglycemic conditions." (PMID 33061796, 2020). "Several recent studies stressed the role of protective effects of UCP2 against the neuronal cell damage after cerebral ischemia and brain trauma; limited studies explored the role of UCP2 in epileptic seizures." (PMID 22849356, 2012). "In this regard, we have demonstrated previously that rosiglitazone, a peroxisome proliferator-activated receptor γ (PPARγ) agonist, enhances UCP2 expression after cerebral ischemia to protect against neuronal cell death in the hippocampus." (PMID 22849356, 2012). "Previous studies have demonstrated that mice transgenically overexpressing UCP2 (UCP2 Tg) in the brain are protected from cerebral ischemia, traumatic brain injury and epileptic challenges." (PMID 22348126, 2012). "Deletion of UCP2 increased ROS production and exacerbated brain injury after middle cerebral artery occlusion in mice, while UCP2 overexpression protected the brain after cerebral ischemia." (PMID 40313775, 2025). "Similarly, the activated PGC‐1α/UCP2 pathway was also validated to be partially responsible for cerebral ischemia‐induced mitochondrial oxidative damage and mitochondria‐dependent apoptosis." (PMID 37206244, 2023). "It has been purposed that SIRT3 activity could be regulated by mitochondrial uncoupling protein 2 (UCP2) during cerebral ischemia-reperfusion injury by increasing the available NAD+/NADH ratio." (PMID 30450031, 2018). "UCP2 may exert a protective effect in myocardial ischemia and cerebral ischemia, while an earlier study indicated that UCP2 accelerates disease progression in amyotrophic lateral sclerosis (ALS)." (PMID 27057102, 2016). "Our recent studies indicated that the PGC-1α–related pathway may enhance mitochondrial proteins UCP2 and superoxide dismutase 2 to counteract excessive reactive oxygen species (ROS) and increase mitochondrial biogenesis in the hippocampus after cerebral ischemia and experimental status epilepticus." (PMID 30823590, 2019). "The impact of UCP2 on mitochondrial morphology of the brain tissue after cerebral ischemia and reperfusion has not been reported." (PMID 33061796, 2020). "However, the impact of UCP2 deletion on mitochondrial fission and fusion balance after cerebral ischemia has not been reported before." (PMID 33061796, 2020).
Cerebral ischemia (continued). "Although we did not establish functional data on UCP2 involvement in protection, our data encourage further study of the temporal aspects of its in vivo expression, together with an evaluation of its expression in other models of cerebral ischemia." (PMID 19772611, 2009).
Hyperinsulinemia (16 papers, 2000 to 2024). An increased concentration of insulin in the blood. "Among the reported Turkish patients, there was no case with exercise-induced hyperinsulinism (SLC16A1), glucokinase-induced hyperinsulinism, or mutations in the UCP2, HNF4A, and HNF1A genes, while one patient had GLUD1 gene mutation." (PMID 27181376, 2016). "Parental-inherited heterozygous UCP2 variants encoding amino-acid changes were found in two unrelated children with congenital hyperinsulinism." (PMID 19065272, 2008). "As a result, whereas the wild type UCP2 inhibits insulin secretion by pancreatic beta cells, the mutated UCP2 promote insulin secretion and as such can explain the hyperinsulinism observed in these patients." (PMID 19065272, 2008). "Recently, loss of function mutations in UCP2 have been described that result in hyperinsulinism." (PMID 23384201, 2013). "Therefore, we report the finding of UCP2 coding variants in human congenital hyperinsulinism, which reveals a role for this gene in the regulation of insulin secretion and glucose metabolism in humans." (PMID 19065272, 2008). "Numerous studies have established a notable correlation between the overexpression of UCP2 and hyperinsulinemia, highlighting its involvement in the development of metabolic disorders." (PMID 37570835, 2023). "In vivo studies observing UCP2 KO mice have shown that these mice develop hyperinsulinism, which suggests that UCP2 is involved in the regulation of insulin secretion." (PMID 27065949, 2016). "For this purpose, we observed that obese BATIRKO mice with moderate hyperinsulinemia had higher UCP-2 levels in aorta and lesser vascular damage than normoinsulinemic obese BATIRKO mice." (PMID 25077985, 2014). "Mutations in eight different genes (ABCC8, KCNJ11, GLUD1, CGK, HADH, SLC16A1, HNF4A and UCP2) have been identified to date in patients with congenital forms of hyperinsulinism (CHI)." (PMID 23032149, 2012). "In this context, we propose to study new molecular mechanisms that help to explain whether the moderate hyperinsulinemia or lowering TNF-α levels might have a protective role against vascular damage mediated by UCP-2 expression levels." (PMID 25077985, 2014). "Thus, 52-week-old control group displaying moderate hyperinsulinemia showed a significant increase in UCP-2 expression levels in the aorta." (PMID 25077985, 2014). "To get a new insight on that UCP-2 protective effect on the vasculature, we have studied new molecular mechanisms that help to explain whether the moderate hyperinsulinemia or reduction TNF-α levels might have a protective role against vascular damage mediated by UCP-2 modulation." (PMID 25077985, 2014).
lung carcinoma (16 papers, 2013 to 2024). "Moreover, upregulation of UCP2 was associated with unfavorable outcome in lung cancer patients, indicating that UCP2 could act as potential diagnostic biomarker for NSCLC." (PMID 38217303, 2024). "Next, we investigate the effects of UCP2 high expression on patients' outcome with lung cancers through Kaplan–Meier Plotter database." (PMID 38217303, 2024). "We downloaded the microarray series data from the TCGA database to determine the expression of UCP2 in lung cancer." (PMID 38217303, 2024). "Here, using data from the TCGA database, in lung cancer samples, we observed the UCP2 expression was increased." (PMID 38217303, 2024). "An upregulation of UCP2 has already been reported for several cancer types, including breast invasive cancer, thyroid carcinoma, lung carcinoma, bladder urothelial cancer, and colorectal adenocarcinoma." (PMID 33614647, 2021). "Our results from cell viability experiments with human lung carcinoma cells as well as analysis of lung carcinoma patient's overall survival reveal a positive impact of UCP2 and PRMT1 on cancer cells." (PMID 29113301, 2017). "It is possible as well that in the lung cancer setting, UCP2 and PRPF40A act upstream of hypoxia pathways, thus inducing expression of HIF1α independently of the O2 tension." (PMID 28258342, 2017). "In previous microarray analyses, COL1A1 and UCP2 were found upregulated in various malignant tissues, including lung cancer." (PMID 28258342, 2017). "Elevated levels of mitochondrial respiration in lung carcinoma cells with combined overexpression of UCP2 and PRMT1 are in line with this suggestion." (PMID 29113301, 2017). "Since viability as well as proliferation of lung cancer cells were strongly affected by expression levels of UCP2 and PRMT1, we analyzed the survival of lung carcinoma patients with different mRNA expression patterns of UCP2 and PRMT1." (PMID 29113301, 2017). "It has previously been shown that the mitochondrial uncoupling protein 2 regulates the ROS/Stat3 signaling pathway and responds to the chemotherapy in lung cancer cells." (PMID 27101310, 2016). "We discovered that high expression level of UCP2 in lung cancer led to worse OS and PFS." (PMID 38217303, 2024). "The result showed that UCP2 was increased in lung cancer tissues." (PMID 38217303, 2024). "However, it is unclear about the mechanism of how UCP2 acts in the tumor growth and metabolic reprogramming process in non‐small cell lung cancer (NSCLC)." (PMID 38217303, 2024). "Furthermore, these results are consistent with a clinical study that showed poorer response to and survival following cisplatin-based chemotherapy in advanced lung cancer patients with low UCP2 expression." (PMID 36499405, 2022). "TRPA1/TRPM8 receptors that have been shown to promote autophagy and the metabolic transformation of UCP2 (uncoupling protein 2), respectively, in Lewis lung cancer (LLC) cells might be responsible for CBD-induced autophagy and modulated ROS levels." (PMID 33921049, 2021). "Hence, UCP2' impact on the MCUC in case of elevated PRMT1 activity is further demonstrated by the poor survival prognosis of lung carcinoma patients with combined upregulation of UCP2 and PRMT1." (PMID 33614647, 2021). "Finally, the authors concluded that UCP-2 and ROS were useful anticancer therapeutic targets in lung cancer." (PMID 33187225, 2020). "Interestingly, high expression of uncoupling protein (UCP)-2 in lung cancer cells under oxidative stress stimulated mitochondrial uncoupling and decreased ROS production." (PMID 33187225, 2020). "Although it is unclear how UCP2 deficiency facilitates the migration of NSCLC cells, the production of ROS, which was found to be increased by UCP2 knockdown, has been demonstrated to expedite metastasis of lung cancer." (PMID 28042952, 2017).
lung carcinoma (continued). "Likewise, progression-free and overall survival of patients with inoperable lung cancer who received cisplatin-based chemotherapy was higher when tumors expressed high levels of UCP2 as compared to tumors with low UCP2 levels." (PMID 23966948, 2013). "The finding that viability and proliferation of lung carcinoma cells was strongly increased in case of upregulated PRMT1 and UCP2 expression further supports a link between the expression of these two proteins and cancer cells’ perilousness." (PMID 29113301, 2017). "Accordingly, in this study we investigated the impact of UCP2 and PRMT1 on the fate of human lung cancer cells (A549, Calu-3 and H1299) as well as on patients suffering from lung carcinoma." (PMID 29113301, 2017). "Furthermore, it has also been shown that the combined overexpression of UCP2 and PRMT1 improved mitochondrial respiration and cell viability in lung carcinoma cells." (PMID 36499405, 2022). "However, there are no reports of circRNA regulating UCP2, with circRNA UCP2 involvement only documented in lung cancer." (PMID 39707176, 2024). "Thus, caution should be taken in correlating the prognosis of cancer progression with UCP2 protein levels in cancer patients, as has been done in breast, pancreatic and lung cancer with non-specific antibodies." (PMID 36499405, 2022).
melanoma (16 papers, 2010 to 2024). A malignant, usually aggressive tumor composed of atypical, neoplastic melanocytes. "Recently, UCP2 downregulation and the resultant increased oxidative stress have been shown to underly the mechanisms of taxol-induced apoptosis of melanoma cells." (PMID 24281083, 2010). "Previous research shows that UCP2 promotes tumorigenesis via enhancing the Akt/mTOR pathway in melanoma." (PMID 38217303, 2024). "Consistently, UCP2 induction sensitizes melanomas to PD-1 blockade treatment and elicits effective antitumor responses." (PMID 37596619, 2023). "Recently, increased UCP2 expression following rosiglitazone treatment in melanoma cell lines promoted antitumor immunity and induced the reprogramming of the cytokine profile secreted by tumor-infiltrating T cells." (PMID 36499405, 2022). "Then, by establishing xenografts with B16-OVA and YUMM1 melanoma cell lines with doxycycline-inducible UCP2 expression, they demonstrated that UCP2 overexpression in these tumor cells induced an immune environment similar to that of melanoma patients." (PMID 36499405, 2022). "Strikingly, Adrβ3 promotes the classical Warburg effect (preferred glycolysis) in melanoma stem cells by upregulating UCP2 (uncoupling protein 2)." (PMID 32477953, 2020). "Using either a genetic or pharmacological approach, induction of UCP2 sensitizes melanomas to programmed cell death protein-1 blockade treatment and elicits effective anti-tumour responses." (PMID 32613561, 2020). "Recently, it has been reported that a role of β3-adrenoreceptors in ROS balancing both in melanoma cells and in glioma cells, respectively controlling Uncoupling Protein 2 (UCP2) and glutathione levels." (PMID 31052299, 2019). "Moreover, evidence suggests that UCP2 enhances anti-tumor immunity in melanoma by reprogramming the immune status of TME." (PMID 35874806, 2022). "Moreover, the downregulation of uncoupler protein 2 (UCP2) expression in melanoma cells has been shown to abrogate chemokine-induced cDC1 tumor infiltration." (PMID 34290401, 2021). "Interestingly, SR59230A inhibited the UCP2 expression in accord with previous data reported in melanoma cells." (PMID 31052299, 2019). "Notably, only UCP2 among the UCPs can induce elevated infiltration of T cells in melanoma." (PMID 35874806, 2022). "That study concluded that the induction of UCP-2, either through genetic modification or a pharmacological approach, resulted in UCP-2 making melanomas cells prone to programmed cell death via protein-1 blockade treatment and thus led to antitumor effects." (PMID 36900198, 2023). "UCP2 induction also significantly improved the response to anti-PD1 immunotherapy, and a greater reduction in tumor volume in melanoma xenografts was reported when anti-PD1 was combined with rosiglitazone." (PMID 36499405, 2022).